EGFR (epidermal growth factor receptor)
Diseases named in the same sentence as EGFR in open-access papers (continued):
Sharing a sentence is not in itself a finding about the gene and the disease.
adenocarcinoma (continued). "EGFR-TKIs as first-line treatment have proved to significantly improve OS and DFS compared to chemotherapy in LA EGFR mutation-positive NSCLC, particularly in patients who are never-smokers, female, or present with adenocarcinoma histology with lepidic growth pattern." (PMID 32722386, 2020). "Early studies found that the mutation frequency of EGFR was lower than other adenocarcinomas (undetectable to ~28% in IMA vs. 47%–78% in non-IMA patients), while the frequency of KRAS mutations was higherin IMA than other adenocarcinomas (14%–86% in IMA vs. 1.5%–17% in non-IMA patients)." (PMID 33505917, 2020). "If the EGFR mutational status of an EBUS-GS specimen is negative, a false-negative should be considered when the sample volume is small, particularly if the patient is at risk of EGFR or ALK mutation (has an adenocarcinoma, is a female East Asian, or is a never-smoker)." (PMID 30807604, 2019). "EGFR mutations were affected significantly more frequently in B7-H3 negative adenocarcinomas than in B7-H3 positive adenocarcinomas, while KRAS mutations were affected significantly more frequently in B7-H3 positive adenocarcinomas than in B7-H3 negative adenocarcinomas (*, p < 0.05)." (PMID 30513627, 2018). "However, our model could represent the portion of human adenocarcinomas negative for KRAS and EGFR mutations." (PMID 29415661, 2018). "In our investigated cohort of triple-negative NSCLCs (EGFR, KRAS, and BRAF mutation negative) the number of cases with either ROS1 or RET fusions were similar to that of ALK-positive cases, supporting the need of multiplexed gene fusion diagnostics in NSCLC and adenocarcinoma specifically." (PMID 28415793, 2017). "Although EGFR mutation was confirmed from a surgical specimen and neither biopsy nor resection of recurrent sites was performed, we captured the LCNEC component and the adenocarcinoma component independently by laser microdissection and confirmed EGFR mutation in both components." (PMID 29312580, 2017). "Furthermore, the detection rates are higher in the selected subgroup for genetic screening based on clinical features commonly associated with ALK-rearrangement, including never or light smoking history, adenocarcinoma histology, and wild-type epidermal growth factor receptor (EGFR) and KRAS status." (PMID 26219569, 2015). "Although we collected enough GGO nodules with EGFR mutations in exons 19 and 21, we could not collect sufficient numbers of samples with ALK rearrangement due to the inherent limitation that adenocarcinoma with ALK rearrangement tends to present as solid nodules in chest CT." (PMID 24885886, 2014). "Multi-omics analyses revealed frequent EGFR and HER3 expression in CRPC adenocarcinoma but not in neuroendocrine subtypes." (PMID 41945392, 2026). "The histopathological examination revealed a poorly differentiated adenocarcinoma, ALK, EGFR, PDL 1 negative, cT3 N3 M1b (OSS, single, right humeral head) and stage IVA." (PMID 40429388, 2025). "Histopathological and immunohistochemical examinations revealed poorly differentiated adenocarcinoma and PDL 1, ALK and EGFR tests were negative." (PMID 40429388, 2025). "HP: poorly differentiated adenocarcinoma, ALK, EGFR negative, cT3N3M1b (OSS, single, right humeral head), stage IVA." (PMID 40429388, 2025). "A bronchoscopy with rebiopsy was practiced on 08/16/2023 and histopathological report and IHC tests from 08/2023 reconfirmed poorly differentiated adenocarcinoma, ALK-negative EGFR-negative and PD-L1 low expression (TPS = 5%)." (PMID 40429388, 2025). "The EGFR- and ALK-targeted cohorts were younger with the highest proportion of adenocarcinoma and never-smokers." (PMID 41139898, 2025). "This is despite the fact that in EGFR/MET mice, the number of full-blown adenocarcinomas was smaller, possibly because of a lack of time to acquire further mutations to promote disease progression." (PMID 34298655, 2021).
adenocarcinoma (continued). "In conclusion, the IdyllaTM method is not suitable for cytological NSCLC adenocarcinoma samples prepared as cytoblocks using AGAR and paraffin embedding of patients with resistance to first and second-generation EGFR TKI’s." (PMID 34344387, 2021). "The histological analysis revealed a poorly differentiated adenocarcinoma, negative for estrogen receptor (ER), progesterone receptor (PgR), human epidermal growth factor receptor 2 (HER-2) and epidermal growth factor receptor (EGFR)." (PMID 29346284, 2018). "ADC=Adenocarcinoma, SCC=Squamous Cell Carcinoma, TN=“Triple Negative” (referring to the absence of alterations in KRAS, EGFR or ALK), I=Immortalized." (PMID 30119639, 2018). "In this study, more than 30% of adenocarcinoma and AIS cases showed strong staining for EGFR, whereas non-neoplastic cervical glands showed no staining or only faint staining." (PMID 28859123, 2017). "In a high-throughput screening program in NSCLC, miR-155 was upregulated only in EGFR/KRAS negative group, miR-25 was upregulated only in EGFR positive group and miR-495 was upregulated only in KRAS positive adenocarcinomas." (PMID 28771186, 2017). "In our study, ALK‐positive patients were younger at diagnosis, and more of them were never smokers and with adenocarcinoma compared with both ALK‐ and EGFR‐negative patients." (PMID 28374971, 2017). "These have recently been described in never smokers with adenocarcinoma that is ALK and EGFR wild type." (PMID 25505733, 2014). "We suggest that responsiveness to EGFR-TKI varies between SCLC and adenocarcinoma, and the SCLC component that did not respond to erlotinib progressed selectively." (PMID 24195468, 2013). "Clinical data suggest that EGFR TKIs gefitinib and erlotinib are more active in certain NSCLC histotypes, such as in adenocarcinomas and bronchioloalveolar carcinomas (BAC), in women, in never smokers and in Asian ethnicity patients." (PMID 20672050, 2010). "Patients with EGFR‐mutant NSCLC tend to be female, nonsmokers, and have adenocarcinoma histology." (PMID 41263395, 2025). "Conversely, LCA inhibitedEphA2 phosphorylation induced by ephrinA1-Fc in PC3 and HT29 human prostate andcolon adenocarcinoma cell lines (IC50 = 48 and66 μM, respectively) without affecting cell viability or other receptortyrosine-kinase (EGFR, VEGFR, IGFR1β, IRKβ) activity." (PMID 21479221, 2011). "The case with the associating adenocarcinoma component showed similar immunohistochemical profile (including EGFR expression) in both tumors, except for the lack of CD56, synaptophysin and chromogranin expressions and the presence of CEA expression in the adenocarcinoma." (PMID 17803816, 2007). "Seventeen studies aimed at predicting EGFR status, one aimed at predicting ALK status, three at predicting both EGFR and KRAS status, one at identifying ALK/ROS1/RET fusion-positive versus fusion-negative adenocarcinomas and two at predicting the PD-L1 expression level." (PMID 32486314, 2020). "While stratifying adenocarcinoma patients into EGFR-mutant and wild-type groups, who were under EGFR-TKI and chemotherapies before diseases progression, respectively, we observed that CEAIn prognostic power was evident only in the EGFR-mutant group but not in the wild-type group." (PMID 32034239, 2020). "However, the levels of C/EBPβ protein were not very different among adenocarcinomas with mutant K-RAS (A549, H23, A427, NCI-H358), mutant EGFR (NCI-H1975, HCC827) and wild-type K-RAS and EGFR (NCI-H1703, NCI-H522, Calu-3), even though A549 and H23 cells displayed relatively high levels of C/EBPβ." (PMID 30754676, 2019).
infection (341 papers, 2008 to 2026). The state of being infected such as from the introduction of a foreign agent such as serum, vaccine, antigenic substance or organism. "Mono-targeting, i.e., infections with oAds encoding either taFv-EGFR or scDb-cMET, required higher virus titers to achieve potent/significant T cell-mediated killing." (PMID 41552759, 2026). "In a mouse model of oral infection, loss of EGFR in epithelial tissues reduced disease severity, suggesting that the receptor helps the fungus establish infection." (PMID 41524399, 2026). "Critically, pharmacological inhibition of TGF-β and EGFR significantly attenuated infection-associated repression of E-cadherin, suggesting that TGF-β signaling in part drives chlamydial induction of EMT in this cell type." (PMID 37265500, 2023). "Taken together, the results demonstrated that activated EGFR is associated with the infection of JEV and ZIKV in hBMECs." (PMID 35847084, 2022). "In this study, we specifically aimed to study the intracellular EGFR dynamics after global desialylation by exogenous sialidase, which can mimic the action of pathogenic sialidases during infection." (PMID 35955894, 2022). "We also showed that HAdV serotypes associated with severe and occasionally fatal infections (e.g., HAdV-E4 and HAdV-B7) provoke a sustained pro-inflammatory EGFR/NF-κB/IL-8 response compared to HAdV-C2/5." (PMID 35083168, 2021). "In this work, we showed that host-cells infection with S. proteamaculans leads to an increase of β1 integrin and EGFR genes expression, and this effect was caused by OmpX interaction with host cells." (PMID 34948042, 2021). "HCMV encodes multiple mechanisms to carefully modulate EGFR signaling pathways during lytic infection as well as during latency and must abrogate this signaling in order to reactivate viral gene expression and enable productive progeny virus production." (PMID 32759334, 2020). "We found that both PDGFRα and EGFR are important for TB40/E infection of human brain organoid, as siRNA-mediated knockdown of either PDGFRα or EGFR completely abrogated the susceptibility of brain organoids to TB40/E." (PMID 33205055, 2020). "In contrast to TNFR1, infection with the RIDα-null virus was sufficient to block EGFR down-regulation independently of other virally-encoded proteins." (PMID 31425554, 2019). "We treated mice for 14 days with the EGFR inhibitor gefitinib and monitored infection-related weight loss of treated and untreated animals to determine if EGFR inhibition affected the course of infection." (PMID 31616667, 2019). "HAdV-C2 infection was also associated with a significant reduction in EGFR metabolic half-life, which typically ranges from 18 to 24 h under basal conditions." (PMID 31425554, 2019). "Following immunoprecipitation with the anti-ACTN4 antibody, we found binding of EGFR to ACTN4 increased significantly in response to PCN033 infection, while contrastingly, the association of cellular actin molecules with ACTN4 decreased markedly." (PMID 30687645, 2018). "EPEC participates in the activation of EGFR and causes the phosphorylation of EGFR, which promotes host cell survival in early infection, but EspF accelerates the loss of EGFR in late infection leading to a dramatic increase in host cell death." (PMID 30524410, 2018). "Currently, the overall incidence and risk of infections with epidermal growth factor receptor (EGFR)-tyrosine kinase inhibitors (TKIs) in non-small-cell lung cancer (NSCLC) patients remained undetermined." (PMID 28107192, 2017). "As a result, clinicians should pay more attention to the risk of infections during the administration of EGFR-TKIs." (PMID 28107192, 2017). "Meta-regression indicated the risk of infections tended to increase with the treatment duration of EGFR-TKIs." (PMID 28107192, 2017). "Recent studies have shown that EGFR plays a role for several pathogenic organisms in the pathogenesis of their infections." (PMID 27711202, 2016).
infection (continued). "During infection, pathogenic Neisseria activates the epidermal growth factor receptor (EGFR) pathway (22, 29, –, 31), and disrupting this pathway reduces the number of viable N. gonorrhoeae cells recovered from within the infected cell." (PMID 27923924, 2016). "We believe that this decrease was due to the change of Cic localization from the nucleus to cytoplasm, which was caused by the activation of EGFR/Ras/MAPK signaling after infection." (PMID 26683696, 2015). "Since EGFR on the host-cell surface interacts with the EB-associated Pmp21 early in infection, we followed its later relationship with C. pneumoniae EBs by indirect immunofluorescence microscopy." (PMID 23633955, 2013). "Conversely, expression of EGFR in normally receptor-deficient cells increased EB attachment and internalization, and susceptibility to infection." (PMID 23633955, 2013). "siRNA-mediated knock-down of EGFR in susceptible cell lines could reduce the infection rate of human H1N1 IAV strain A/Puerto Rico/8/34 (PR8) by about 60%11." (PMID 40280912, 2025). "On the other hand, various viral and bacterial sialidases can cleave α-2,3, α-2,6 or α-2,8 sialosides on membrane-associated glycoconjugates and could affect EGFR signaling during their infection." (PMID 35955894, 2022). "We assessed whether dysregulated EGFR signaling caused by ZNRF1 deficiency enhances HSV-1 entry during early infection." (PMID 33996800, 2021). "EGFR signaling has recently been shown to participate in innate immune signaling including Toll-like receptors (TLRs) to promote host defense against pathogenic infection." (PMID 33996800, 2021). "To better understand the underlying mechanisms involved in PICD and to investigate whether the difference in PICD could be caused by a differentially regulated AREG/EGFR signaling, we used a well-established in vitro infection model." (PMID 30524196, 2018). "Moreover, we perform a meta-regression analysis to assess the relationship between EGFR-TKIs treatment duration and risk of infections." (PMID 28107192, 2017). "Similarly, the use of EGFR-TKIs alone had a tendency to increase the risk of all-grade infections when compared to placebo (Peto OR 2.24, 95%CI: 0.27-18.53, p = 0.45) or chemotherapy alone (Peto OR 1.93, 95%CI: 0.88-4.26, p = 0.10)." (PMID 28107192, 2017). "The use of EGFR-TKIs significantly increased the risk of developing all-grade infections (Peto OR 1.48, 95%CI: 1.12-1.96, p = 0.006) in NSCLC patients, but not for severe (Peto OR 1.26, 95%CI: 0.96-1.67, p = 0.098) and fatal infections (Peto OR 0.81, 95%CI: 0.43-1.53, p = 0.52)." (PMID 28107192, 2017). "However, more high-quality research are still recommended to determine the mechanisms of EGFR-TKIs associated infections." (PMID 28107192, 2017). "However, the data showed that the expression of mRNA encoding EGFR was significantly downregulated as a result of the infection with P. gingivalis." (PMID 28748038, 2017). "Finally, we carried out a meta-regression analysis to investigate the association between Peto OR of all-grade infections and the length of EGFR-TKIs treatment." (PMID 28107192, 2017). "In the meantime, awareness of the role of EGFR-directed antibodies in increased infection risk may have implications for dose modification strategies in both clinical trial design and the practice of oncology." (PMID 25857245, 2015). "Further studies are needed to better identify the association between EGFR-directed monoclonal antibody treatment and infection, as well as to elucidate the mechanism of this toxicity and to develop tools to identify patients at increased risk for these complications." (PMID 25857245, 2015).
infection (continued). "The present study aimed to investigate if immunohistochemical expressions of EGFR, pEGFR and p16, could predict infection with high risk HPV in HIV-related SCCC." (PMID 24572046, 2014). "Importantly, our findings suggest a direct dependence between the levels of EGFR on the cell surface and susceptibility to infection by C. pneumoniae." (PMID 23633955, 2013). "The JAK-STAT and EGFR pathways in ISCs and the EGFR pathway in enterocytes are indispensable for maintaining homeostasis, as flies lacking those pathways in the corresponding cells are highly susceptible to infection." (PMID 24381562, 2013). "Thus, our studies suggest that the effects of MIC deficiency on the levels of EGFR-Akt activation likely explain the differences in outcome observed after infection." (PMID 24367261, 2013). "For example, analysis of an arenavirus network, built around gene products differentially expressed in virulent and avirulent LCMV infections of rhesus macaques, highlighted a potential role for the epidermal growth factor receptor EGFR in infection by pathogenic arenaviruses." (PMID 23342371, 2012). "Interestingly, our survival analysis points to a key role of EGFR-mediated enterocyte morphogenesis in the maintenance of the integrity of the gut, as shown by the increased susceptibility of EGFR-deficient flies to infection." (PMID 21176204, 2010). "Consequently, it is plausible that blocking EGFR could substantially diminish infection rates, particularly in variants." (PMID 39291996, 2024). "Furthermore, inhibition of EGFR impairs candidalysin-triggered MAPK signalling and release of neutrophil activating chemokines in vitro, and diminishes neutrophil recruitment, causing significant mortality in an EGFR-inhibited zebrafish swimbladder model of infection." (PMID 31127085, 2019). "Strikingly, this mechanism operated not only for meningitic E. coli, but also for infections with Streptococcus suis, a Gram-positive meningitis-causing bacterial pathogen, thus revealing a common mechanism hijacked by these meningitic pathogens where EGFR competitively recruits ACTN4." (PMID 30687645, 2018). "However, whether the use of EGFR-TKIs would increase the risk of infections in NSCLC remains undetermined." (PMID 28107192, 2017). "In addition, we conducted sub-group analysis based on treatment regimens, and demonstrated that the addition of EGFR-TKIs to chemotherapy had a tendency to increase the risk of infections in comparison with chemotherapy alone (Peto OR 1.24, 95%CI: 0.75-3.05, p = 0.39)." (PMID 28107192, 2017). "For example, the Db-TriTE was stronger expressed after infection of SW480 cells with Ad5/3-DMFE than the taFv-EGFR after infection with Ad5/3-tE." (PMID 41552759, 2026). "A key step in infection is the fungus invading epithelial tissues and activating the host epidermal growth factor receptor (EGFR)." (PMID 41524399, 2026). "Our analysis revealed stage-specific signatures: NILM displayed a "stealth infection" profile marked by upregulated protein synthesis and growth signaling (EGFR/ERBB2) alongside immune suppression." (PMID 41855211, 2026). "Our observations indicated a negligible level of EGFR activation in both mock and vΔVGF conditions when compared with infections with WT-VACV, substantiating the essential role of VGF in EGFR activation." (PMID 39817770, 2025). "Epidermal growth factor receptor (EGFR) signaling emerges as a regulator of macrophage responses to infection, particularly in the gut, suggesting its potential as a therapeutic target for chronic gut inflammation." (PMID 41304898, 2025). "Collectively, pharmacological inhibition of EGFR with both broad-spectrum and specific inhibitors was detrimental for virus entry and infection." (PMID 41401233, 2025).